ANXA2 (annexin A2)
Diseases named in the same sentence as ANXA2 in open-access papers (continued):
Sharing a sentence is not in itself a finding about the gene and the disease.
Stroke (15 papers, 2009 to 2025). Sudden impairment of blood flow to a part of the brain due to occlusion or rupture of an artery to the brain. "Although our review of the literature does not suggest that his infarct can be explained by the factor V Leiden heterozygosity, he was not tested for any of the other genetic variants that have been recently found to be associated with stroke in SCD such as ANXA2, TGFBR3, and TEK." (PMID 23972124, 2013). "Also, there have been a few single nucleotide polymorphisms (SNPs) in persons with SCD that have been found to be associated with increased stroke risk: ANXA2, TGFBR3, and TEK were noted in a study including these SNPs." (PMID 23972124, 2013). "On the one hand, Anxa2 overexpression significantly improved sensorimotor function, which was prominent on day 14 after stroke." (PMID 39912333, 2025). "Although these studies did not focus exclusively on SC strokes, their results agree with ours in that ANXA2 levels are elevated in patients with SC stroke compared with HCs." (PMID 34356850, 2021). "SNPs in the ANXA2, TEK and TGFBR3 gene loci were associated with stroke risk, the TGF-β/BMP pathway is associated with several SCD subphenotypes, while polymorphisms within the UGT1A1 are associated with increased serum bilirubin levels and cholelithiasis." (PMID 34071035, 2021). "Previous studies have shown an increased ANXA2 expression after stroke in patients and in vitro studies." (PMID 34356850, 2021). "The combined application of Annexin A2 and t-PA decreased the effective thrombolytic dose of tPA, reduced hemorrhage and brain infarction, and prolonged the reperfusion time window for stroke." (PMID 29681849, 2018). "Five single nucleotide polymorphisms (SNPs) tested in children with SCD were significantly associated with stroke risk, namely ANXA2 (rs11853426), TEK (rs489347), and TGFBR3 (rs284875) variants, whereas ADCY9 (rs2238432) and ∝ -thalassemia were linked with decreased stroke risk." (PMID 35781614, 2023). "They suggest that these model variants in BMP6 are the strongest risk factors, whereas variants in EDN1 are associated with stroke through BMP6 and ANXA2 but are not as relevant for the risk prediction." (PMID 20401335, 2009). "Potential pathological factors contributing to inadequate tPA recanalization in stroke patients include elevated levels of plasminogen activator inhibitor 1 (PAI-1), atherosclerotic vascular damage due to diabetes, glycation of the tPA receptor annexin A2, and alterations in fibrin clot density." (PMID 41291553, 2025).
antiphospholipid syndrome (14 papers, 2012 to 2025). A disorder caused by the presence of autoantibodies directed against phospholipids, causing a hypercoaguable state, which may result in blood clots, stroke, heart attack, and in women, significant pregnancy-related complications, including miscarriage and still birth. "Dysregulation of ANXA2 is tightly associated with a broad spectrum of prevalent diseases, involving autoimmune and neurodegenerative diseases, antiphospholipid syndrome, diabetes mellitus, and different malignant tumors." (PMID 34055578, 2021). "Anti-ANXA2 antibodies have been detected in the serum of patients with RA and could provide a certain degree of diagnostic value for concomitant antiphospholipid syndrome." (PMID 38141769, 2023). "Other AnxA2-related aspects in vascular homeostasis and angiogenesis include the high AnxA2 antibody titers associated with thrombotic complications in cerebral venous thrombosis as well as the antiphospholipid syndrome." (PMID 33810523, 2021). "However, AAbs to annexin A2 have also been reported in the context of anti-phospholipid syndrome, sometimes in association with cancer." (PMID 26774260, 2016). "ANXA2, likely via its complexation with β2-glycoprotein I, is involved in the pathogenesis of an autoimmune disease, antiphospholipid syndrome, characterized by arterial, venous or small-vessel thrombotic events, and recurrent miscarriages or fetal loss." (PMID 32824294, 2020). "Curiously, although the levels of ANXA2 are increased in antiphospholipid syndrome, ANXA5 is under-expressed in this disease." (PMID 32824294, 2020). "Antibodies against annexin A2 in antiphospholipid syndrome, together with inhibition of plasmin release, promote thrombus formation; of note, 20% of CTEPH patients carry antiphospholipid antibodies." (PMID 33270690, 2020). "Autoantibodies targeting ANXA2 have been previously found in antiphospholipid syndrome (APS)." (PMID 38913740, 2024). "Annexin A2, a Ca2+-regulated membrane binding protein with key roles in membrane-cytoskeleton and membrane-membrane binding events, has been shown to be an autoantigen in several immune-mediated diseases including anti-phospholipid syndrome and rheumatoid arthritis (RA)." (PMID 33043033, 2020).
liver fibrosis (14 papers, 2013 to 2026). "By integrating RNA-sequencing with multiple hepatic fibrosis database analysis and correlation analysis, we identified Annexin A2 (ANXA2) as a cholesterol-responsive gene associated with fibrosis." (PMID 42188041, 2026). "Previous studies have demonstrated that upregulation of ANXA2 is associated with liver fibrosis and can be useful as a biomarker for hepatitis B virus-related liver fibrosis." (PMID 32154257, 2020). "Several previous studies have demonstrated that ANXA2 is differentially expressed between normal tissues and tissues of liver fibrosis induced by various causes (e.g. alcohol, the immune system or HBV)." (PMID 23946789, 2013). "Our previous work identified S100A10 as a MASLD promoter, suggesting that its association with AnnexinA2 (ANXA2) within the S100A10-ANXA2 heterotetramer (A2t) might promote hepatic fibrosis." (PMID 42271090, 2026). "In addition, increased ANXA2 expression in hepatocytes promotes MASH-associated hepatic fibrosis by increasing the expression of osteopontin." (PMID 40717977, 2025). "In addition, ANXA2 has been demonstrated to be a potential biomarker of immune liver fibrosis in a rat liver fibrosis model, indicating that ANXA2 may also be associated with liver fibrosis or even cirrhosis." (PMID 23946789, 2013). "Specifically, the ANXA2-Notch regulatory loop plays a crucial role in promoting liver fibrosis in NAFLD by modulating osteopontin expression." (PMID 39697329, 2024). "ANXA2 is not only involved in liver fibrosis and hepatocarcinogenesis but also shows potential as a diagnostic biomarker, making it a significant focus in current liver disease research." (PMID 39697329, 2024). "ANXA2 influences liver fibrosis through its interactions with cellular pathways that regulate extracellular matrix remodeling." (PMID 39697329, 2024). "ANXA2 expression was found to be positively associated with the course of NAFLD and increased along with liver fibrosis in human samples." (PMID 38192427, 2023). "The increased expression of ANXA2 in hepatocytes can promote hepatic fibrosis in NASH mice, and the mechanism was to increase the expression of osteopontin." (PMID 36324154, 2022). "Here, we provide in vivo and in vitro evidence that Anxa2 promotes hepatocyte pyroptosis and liver fibrosis." (PMID 36324154, 2022). "In this study, we first involved the GEO database for identifying ANXA2 as a liver fibrosis-related gene, which has so far been rarely discussed." (PMID 36324154, 2022). "Meanwhile, inhibiting the overexpression of Anxa2 can significantly improve hepatocyte pyroptosis and liver fibrosis, either in NASH mice in vivo or LPS-induced hepatocytes in vitro." (PMID 36324154, 2022). "Masson and immunohistochemical staining revealed that, overexpression of Anxa2 aggravated liver fibrosis in NASH mice, and this pro-fibrotic effect was significantly reversed by the inhibition of Caspase-1." (PMID 36324154, 2022). "EPHB2 and ANXA2 are related to hepatic fibrosis that is not only a prominent feature of BA but also a good predictor of outcome in mice following portoenterostomy." (PMID 32848883, 2020). "It is reported that the serum level of ANXA2 was found to be elevated in liver fibrosis cases companied with chronic hepatitis B virus, and was considered as a candidate bio-marker for liver fibrosis." (PMID 27533088, 2016). "Moreover, ANXA2 manifested in a cluster positively correlated with the stage of liver fibrosis (F0-F4) in our human dataset, indicating its importance in the progression of NAFLD, especially during fibrosis." (PMID 38192427, 2023). "ANXA2 expression gradually increased with increasing feeding time on a high-fat diet in mouse samples, and in human samples, its expression was also upregulated with the severity of liver fibrosis stage." (PMID 38192427, 2023).
liver fibrosis (continued). "Not only that, ANXA2 may also promote hepatic stellate cell activation and collagen fibril synthesis by participating in the Anxa6/miR-9-5p/Anxa2 pathway or increasing the expression of osteopontin, thus leading to the onset and acceleration of hepatic fibrosis." (PMID 38192427, 2023). "ANXA2 was significantly upregulated in HBV and alcohol-induced liver fibrosis." (PMID 40717977, 2025). "Taken together, the evidence suggested that ANXA2 may be involved in early-stage HCC development, i.e., liver fibrosis to cirrhosis progression." (PMID 34575275, 2021). "Additionally, the mouse ANXA6/miR-9-5p/ANXA2 axis, along with the PI3K/Akt signaling pathway, may play a role in promoting liver fibrosis mediated by lncRNA ANXA2P2." (PMID 40717977, 2025). "However, whether ANXA2 can be used as a noninvasive biomarker in HBV and alcohol-induced liver fibrosis deserves further investigation." (PMID 40717977, 2025).
pancreatic ductal adenocarcinoma (14 papers, 2013 to 2024). An infiltrating adenocarcinoma that arises from the epithelial cells of the pancreas. "Latest studies highlighted the role of ANXA2 expression in cancer-associated fibroblasts in stromal tissue in pancreatic ductal carcinoma and epithelial ovarian cancer as a predictive biomarker for overall survival." (PMID 32671503, 2020). "Pancreatic ductal adenocarcinoma (PDAC) associated antigen Annexin A2 (ANXA2)-expressing Lm could activate CD8+ T cells in TME and improve the survival of the rodent models of PDAC." (PMID 37868979, 2023). "For example, ANXA2 Y24, a SRC-regulated site, has recently been reported to correlate with invasiveness and metastatic events in pancreatic ductal adenocarcinoma, underlining the established role of MET in driving invasive growth during tumorigenesis." (PMID 36494469, 2022). "Previous studies have confirmed that miR-23b-3p could bind specifically to the 3’ untranslated region of ANXA2 in pancreatic ductal adenocarcinoma." (PMID 38102461, 2024). "Furthermore, AnxA2 antibodies inhibit pancreatic ductal adenocarcinoma metastases, thus prolonging survival." (PMID 23555942, 2013). "It was also reported that in pancreatic ductal adenocarcinoma (PDA) cells, cell-surface annexin A2 promotes cancer cell invasion and metastasis upon binding with the extracellular matrix component tenascin C (TNC)." (PMID 37091157, 2023). "In pancreatic ductal adenocarcinoma (PDA), AnxA2 can promote the secretion and thereby increase the levels of SEMA3D, and primary PDA patients that express high levels of SEMA3D have a wider range of metastases than those who express lower levels of SEMA3D." (PMID 28320475, 2017). "MiR-206 has been reported as a tumor suppressor gene in human pancreatic ductal adenocarcinoma (PDAC), directly targeting oncogenes KRAS and annexin a2 (ANXA2)." (PMID 27191262, 2016). "They showed that miR-206 suppressed the pancreatic ductal adenocarcinoma cell cycle progression, migration, invasion and proliferation by targeting KRAS and annexin a2 (ANXA2)." (PMID 27906963, 2016).
bladder cancer (13 papers, 2016 to 2025). "AnxA2 expression significantly mobilized to the surface of highly metastatic bladder cancer cells compared to cells derived from low-grade tumors and associated with high plasmin generation and AnxA2 secretion." (PMID 36428758, 2022). "We found that the AnxA2 protein was upregulated in bladder cancer cells derived from high-grade tumors and also associated with higher secretion in the media." (PMID 36428758, 2022). "In conclusion, our results demonstrated that high expression of AnxA2 promotes proliferation, migration, and invasion in bladder cancer cells, and AnxA2 mRNA expression was significantly associated with the poor prognosis of BLCA patients." (PMID 36428758, 2022). "Our results further confirm that high expression of AnxA2 is significantly associated with the aggressive phenotype of bladder cancer." (PMID 36428758, 2022). "Our analysis confirmed that a high expression level of AnxA2 was noticeably associated with high tumor stage and grade and an unfavorable prognosis of bladder cancer." (PMID 36428758, 2022). "A high abundance of AnxA2 was noticeably associated with high grade and stage and aggressive histologic grade bladder cancer and revealed poor prognosis in bladder cancer patients." (PMID 36428758, 2022). "AnxA2-mediated plasmin generation assay was performed to examine whether an increased cell surface pool of AnxA2 in bladder cancer cells is associated with an extensive production of plasmin." (PMID 36428758, 2022). "mtiRL enhances the binding of ANXA2 to Yes1 and facilitates the phosphorylation of ANXA2 at Tyr24, thereby stimulating the proliferation and metastasis of bladder cancer cells." (PMID 40265011, 2025). "It has also been reported that ANXA2 is highly expressed in bladder cancer tissues, and inhibiting ANXA2 can enhance the sensitivity of bladder cancer to doxorubicin, thereby improving the efficacy of chemotherapy." (PMID 40481236, 2025). "Subsequent studies revealed that mtiRL promotes bladder cancer metastasis by binding to the ANXA2 protein." (PMID 40265011, 2025). "By reducing ANXA2 expression in bladder cancer T24 cells using RNA interference (RNAi), the authors found that knocking down the ANXA2 gene significantly inhibited the proliferation, migration, and invasion of T24 cells." (PMID 39057791, 2024). "Several studies have used MRM to obtain detailed expression profiles of sEV proteins and to identify potential biomarkers such as HSP90 and syndecan-1 in bladder cancer, and annexin A2 and clusterin in Alzheimer's disease." (PMID 36797736, 2023). "Annexin A2 is a potential biomarker for predicting drug resistance and recurrence of bladder cancers." (PMID 36428758, 2022). "In vitro assays demonstrated that depletion of AnxA2 significantly inhibited the proliferation, metastasis, and invasion of bladder cancer cells by downregulating the expression of proangiogenic proteins and cytokines." (PMID 36428758, 2022). "The high secretion of AnxA2 from T24 cells was significantly observed with aggressive subtypes of bladder cancer." (PMID 36428758, 2022). "On this basis, we explore the effects of AnxA2 on bladder cancer cell proliferation by performing the MTT assay." (PMID 36428758, 2022). "We also analyzed the cell surface levels of AnxA2 in bladder cancer cells by conjugating all cell surface proteins with membrane-impermeable biotin and immobilizing them with streptavidin-linked beads." (PMID 36428758, 2022). "Our results provide a strong case for AnxA2 as a potential prognostic predictor with poor clinical outcomes for bladder cancer patients." (PMID 36428758, 2022). "Secondly, we must determine how AnxA2 promotes bladder cancer cell proliferation, migration, and invasion." (PMID 36428758, 2022). "To elucidate the biological functions of AnxA2, we down-regulated the expression of AnxA2 in the bladder cancer T24 cells." (PMID 36428758, 2022).
bladder cancer (continued). "ANXA2 expression in adriamycin-resistant bladder cancer cell line was significantly higher than that in normal bladder epithelium." (PMID 34048174, 2021). "The role of ANXA2 expression in the acquisition of drug resistance is of interest, but there were few reports of ANXA2 expression in bladder cancer." (PMID 34048174, 2021). "ANXA2 overexpression in bladder cancer tissues was significantly correlated with invasion depth and shorter recurrence-free survival." (PMID 34048174, 2021). "In the present study of bladder cancer, ANXA2 expression was significantly correlated with P-glycoprotein expression and was closely related with IVR." (PMID 34048174, 2021). "In recent years, it has been found ANXA2 plays critical roles in bladder cancer formation, progression, and recurrence." (PMID 31695759, 2019). "Moreover, METTL1-mediated m7G-3′-tiRNA LysTTT promoted bladder cancer malignancy by binding to ANXA2 to enhance its phosphorylation by Yes1." (PMID 40045194, 2025). "However, the expression of urokinase plasminogen activator surface receptor (uPAR) was found to be upregulated in AnxA2 knockdown T24 bladder cancer cells." (PMID 36428758, 2022). "Together, these results further established that high mRNA expression of AnxA2 might contribute to the tumorigenesis of BLCA and be an essential risk factor for the poor clinical outcome of bladder cancer patients." (PMID 36428758, 2022). "Transwell assays were performed to examine the role of AnxA2 in bladder cancer cell invasion." (PMID 36428758, 2022). "Consistent with previous studies, we also found that AnxA2 knockdown significantly inhibited bladder cancer cell proliferation, migration, and invasion, along with remarkably decreased expression of proangiogenic proteins such as PDGF-BB, ANGPT1, ANGPT2, Tie-2, bFGF, GRO, IL-6, IL-8, and MMP-9." (PMID 36428758, 2022). "In addition, the expression and function of AnxA2 were evaluated by downregulating AnxA2 in bladder cancer cells." (PMID 36428758, 2022). "Similarly, we found that AnxA2 expression was higher in bladder cancer cells derived from high-grade metastatic carcinoma than in cells derived from low-grade urothelial carcinoma." (PMID 36428758, 2022). "The role of AnxA2 in T24 bladder cancer cell migration was assessed using the wound healing assay." (PMID 36428758, 2022). "The interaction between ANXA2 and P-glycoprotein may be related to resistant mechanism against adriamycin in clinical samples of bladder cancer." (PMID 34048174, 2021). "ANXA2 overexpression was seen in an adriamycin-resistant bladder cancer cell line." (PMID 34048174, 2021). "In clinical samples of bladder cancer, ANXA2 expression in T2 group was higher than ANXA2 expression in Tis-T1 group and ANXA2 expression in patients who recurred at < 6 months after initial surgery was significantly higher than ANXA2 expression in patients who recurred at > 2 years." (PMID 34048174, 2021). "In this study, we selected four hypoxia-related genes that were highly related to bladder cancer patients’ survival status, including ANXA2, GALK1, COL5A1, and HS3ST1, to construct a signature and this signature is independent of other clinical characteristics." (PMID 34026819, 2021). "In addition, we have further examined whether increased expression of AnxA2 in bladder cancer mobilizes it to the outer membrane." (PMID 36428758, 2022). "In addition, the downregulation of AnxA2 cells significantly inhibited the proliferation, migration, and invasion in bladder cancer along with the reduction in proangiogenic factors and cytokines such as PDGF-BB, ANGPT1, ANGPT2, Tie-2, bFGF, GRO, IL-6, IL-8, and MMP-9." (PMID 36428758, 2022). "In this study, we aim to evaluate the significance of AnxA2 in BLCA and establish its metastatic role in bladder cancer cells." (PMID 36428758, 2022). "Overexpressions of ANXA2 and NPM were identified in adriamycin-resistant human bladder cancer cell lines by proteome analysis." (PMID 34048174, 2021).